BAP1 (BRCA1 associated deubiquitinase 1)
Diseases named in the same sentence as BAP1 in open-access papers (continued):
Sharing a sentence is not in itself a finding about the gene and the disease.
uveal melanoma (continued). "BAP1 gene is often mutated in cases of uveal melanoma, which accounts for 3–5% of all diagnosed melanomas." (PMID 35465855, 2022). "The strongest genetic risk factor for metastasis in uveal melanoma is the mutational inactivation of the BAP1 tumor-suppressor gene." (PMID 35954340, 2022). "A large proportion of uveal melanomas also bear loss-of-function mutations of BRCA1-associated-protein-1 (BAP-1)." (PMID 35409020, 2022). "Germline mutations in BAP1 increase the risk for a new tumor predisposition syndrome characterized by several tumors, including uveal melanoma." (PMID 35563772, 2022). "Genetic changes associated with BAP1 have been linked to increased metastatic behavior in uveal melanoma." (PMID 36292588, 2022). "Either monosomy 3 or a somatic knock-out of the second BAP1 allele leads to BAP1 inactivation in approximately 35–45% of all uveal melanomas and confers the worst prognosis of these three key driver genes." (PMID 34195690, 2021). "BAP1 germline mutations have been suggested to predispose patients to developing uveal melanoma, cutaneous melanoma, and other malignancies, including mesothelioma and renal cell carcinoma." (PMID 35008286, 2021). "Mutations in BAP1 are associated with cutaneous melanoma, uveal melanoma, and other internal malignancies such as mesothelioma and renal cell carcinoma." (PMID 34638397, 2021). "Here, we show that assessment of BAP1 methylation is an accurate and readily clinically actionable assay to accurately identify high-risk uveal melanoma patients." (PMID 34593944, 2021). "BAP1 mutations have high risk of metastasis and occur in ~50% of uveal melanoma and typically result in metastasis within 5 years." (PMID 34298647, 2021). "BAP1 gene mutation has a strong association with both the presence of uveal melanoma and an increased risk of metastasis." (PMID 34771510, 2021). "In support of this interpretation, recent findings reveal that low BAP1 expression is associated with longer survival in cutaneous melanoma, but shorter survival in uveal melanoma." (PMID 32944962, 2021). "First implicated in the development of malignant mesothelioma and uveal melanoma, germline BRCA1-associated protein-1 (BAP1) mutations are a relatively recently discovered tumor predisposition syndrome." (PMID 33670168, 2021). "BAP1 (BRCA1-Associated Protein 1) gene mutation is one of the strongest predictors for metastasis in uveal melanoma." (PMID 34771510, 2021). "We conclude that BAP1 mutations occur early in the growth of uveal melanoma, well before the average tumor is diagnosed." (PMID 33903674, 2021). "In this study, we investigated a variety of therapeutic compounds in primary-derived uveal melanoma cell lines and found monosomy of chromosome 3 (M3) and mutations in BAP1 to be associated with higher resistance to MEK inhibition." (PMID 34201614, 2021). "This highlights another aspect of intratumor heterogeneity in uveal melanoma BAP-1 expression: even if loss of BAP-1 expression is a very strong prognostic factor per se, mutant tumor still need a means of intravasating and exiting the eye." (PMID 33800007, 2021). "This aspect is of particular relevance given that BAP1 mutations are generally associated with a worse prognosis for patients with cutaneous melanoma, uveal melanoma and renal cell carcinoma." (PMID 34442055, 2021). "BAP1 deletion in the primary tumor is associated with uveal melanoma metastasis, but it cannot always be resolved by bulk DNA sequencing of heterogeneous tumors." (PMID 34593944, 2021). "Germline mutations of BAP1 have been associated with hereditary predisposition to multiple cancers, including uveal melanoma (UM) and cutaneous melanoma (CM)." (PMID 33800394, 2021). "PMEL is a co-expression gene with BAP1 (BAP1 loss is common in uveal melanoma UM and is associated with a worse prognosis)." (PMID 34722301, 2021).
uveal melanoma (continued). "Breast cancer type 1 susceptibility protein (BRCA1)‐associated protein (BAP1) is a marker of poor prognosis in several cancers, including uveal melanoma, renal cell carcinoma, cholangiocarcinoma, non‐small cell lung cancer, and colorectal cancer." (PMID 33529461, 2021). "Based on our molecular findings, CM comprises a separate entity within melanoma, although there are overlapping molecular features with uveal melanoma, such as the presence of BAP1 and SF3B1 mutations." (PMID 34071371, 2021). "Skin examinations every six months should be conducted, and patients with a known BAP1 mutation should have MBAITs removed as well as other lesions that change with time, along with ophthalmologic screening every year to monitor for uveal melanomas." (PMID 34638397, 2021). "Germline mutations in BAP1 have been identified in families with “BAP1 cancer syndrome”, characterized by the predisposition to developing benign atypical melanocytic lesions, uveal melanomas, and MPM." (PMID 34070352, 2021). "In Uveal Melanoma (UM), an inflammatory phenotype is strongly associated with the development of metastases and with chromosome 3/BAP1 expression loss." (PMID 34439300, 2021). "Germline mutations of BAP1 have also been identified, suggesting a hereditary form of uveal melanoma." (PMID 32429485, 2020). "Inactivating mutations in BAP1, a tumor suppressor gene located on chromosome 3p, are found in approximately 47% of primary uveal melanoma and 84% of metastatic uveal melanoma cases, consistent with the association between BAP1 mutations and poor prognosis." (PMID 32894202, 2020). "Autosomal dominant inheritance of pathogenic BAP1 gene variants have been observed in 47% of uveal melanomas, while pathogenic EIF1AX variants have been found in 14–20% of the cases." (PMID 32321466, 2020). "Germline mutations in the BAP1 gene have also been associated with BAP1-tumor predisposition syndrome which carries an increased risk of developing uveal melanoma, cutaneous melanoma, malignant mesothelioma, RCC, meningioma, and cholangiocarcinoma." (PMID 32197306, 2020). "Multiple other studies since have confirmed the correlation of BAP1 mutations with metastasis, tumor aggression, and worse prognosis in uveal melanoma." (PMID 32429485, 2020). "Only 2–4% of all uveal melanoma patients harbor a germline BAP1 mutation and although familial uveal melanoma is rare, BAP1 has been identified as a predisposition gene for UM as well as a variety of other cancers." (PMID 33396957, 2020). "At the same time, BAP1 mutation is strongly associated with a more aggressive, metastatic phenotype in uveal melanomas." (PMID 33585209, 2020). "This agrees with other reports that questioned the efficacy of PRC2 inhibition showing that viability of BAP1-deficient uveal melanoma cells is largely unaffected by PRC2 inhibition." (PMID 31883952, 2020). "As a result, determining BAP1 status in cases of uveal melanoma can be useful to understanding the risk of metastasis." (PMID 32429485, 2020). "Most importantly, tumors with loss‐of‐function BAP1 mutations carry the worst prognosis, as approximately 84% of metastatic uveal melanomas are of this subtype." (PMID 31880399, 2020). "Germline BAP1 mutations were rarely identified in Czech patients so far, dominantly in probands with uveal melanoma or Spitz nevi." (PMID 33050356, 2020). "These cell lines originate from primary uveal melanoma tumours, possess a loss of heterozygosity of chromosome 3, and show BAP1 protein expression." (PMID 32299493, 2020). "In fact, BAP1 is the most common mutation found in familial uveal melanoma, with an estimated frequency of 8%–50% of such cases." (PMID 32429485, 2020). "The inflammatory phenotype of primary uveal melanoma is associated with monosomy 3 and BAP-1 loss that are known high-risk genetic occurrences in uveal melanoma predictive of metastasis." (PMID 33317028, 2020).
uveal melanoma (continued). "Hereditary BAP1 mutations predispose people to hypopigmented skin melanoma, uveal melanoma, mesothelioma, renal cell carcinoma, and other cancers." (PMID 33050356, 2020). "BAP1-associated uveal melanomas are diagnosed in the age of 30–59 years and are associated with cutaneous melanomas and renal cell carcinomas, while EIF1AX gene variants are associated with thyroid and ovarian cancer." (PMID 32321466, 2020). "It is known that chromosome 3 monosomy and the loss of BAP1 expression are related to poor prognosis and an increased risk of developing metastatic disease in uveal melanoma." (PMID 32131485, 2020). "These mutations are specific to uveal melanoma as is BAP1 protein, which is considered to be a marker of metastatic disease." (PMID 32299493, 2020). "These include discovery of the major driver mutations in uveal melanoma, and prognostic factors for metastatic spread, including monosomy 3 and BAP1 mutation." (PMID 31320995, 2019). "Germline mutations in the breast cancer 1 (BRCA1)-associated protein-1 (BAP1) gene were found in highly metastatic uveal melanoma and later also in familial cutaneous melanoma." (PMID 31717496, 2019). "Monosomy of chromosome 3 often co-occurs with mutation of the BAP1 gene in 3p21.1, results in bi-allelic inactivation and is a hallmark of uveal melanoma with unfavorable prognosis." (PMID 31748560, 2019). "Our study demonstrated that our densely-connected deep learning model can be used to assist in the diagnostic evaluation of nuclear BAP1 expression in the uveal melanoma from histopathology slides." (PMID 31623293, 2019). "In uveal melanoma cells, BAP1 knockdown causes G1 arrest most likely through HCF1-mediated effects that involve histone deubiquitination and effects on E2F1-dependent transcription." (PMID 30669483, 2019). "Particularly, in uveal melanoma (UM), the most frequent intraocular tumor of the eye, BAP1 mutations were identified in 84% of tumors with a metastasizing phenotype." (PMID 31635116, 2019). "At first, somatic BAP1 mutations were identified in 84% of 31 analyzed metastasized uveal melanoma (UM) and these mutations were found to be associated with metastatic progression of UM." (PMID 31382694, 2019). "Low nuclear immunohistochemical positivity for BAP1 has been shown to provide significant prognostic information in uveal melanoma and gain equal-level reliability with gene mutation assays." (PMID 31623293, 2019). "Considering the Harrell’s C indices for MYC copy number gain and BAP1 mutation, we think that both factors affect survival outcomes of uveal melanoma patients independently." (PMID 31848373, 2019). "BAP1 mutations were identified in 28% uveal melanoma patients, and the types of mutations included frame shift deletion, missense mutation, nonsense mutation, splice site and frame shift insert." (PMID 31598164, 2019). "Loss of BAP1 due to mutations and deletions has been reported in various cancers including lung, renal, breast, uveal melanoma, and MMe." (PMID 30669483, 2019). "Herein, we focused specifically on uveal melanoma (UM) in which BAP1 mutations are associated with a metastasizing phenotype and decreased survival rates." (PMID 31635116, 2019). "In uveal melanoma, BAP1 mutations cause cell phenotype modifications, which are associated with metastatic disease in 84% of patients and class 2 genetic features (with high metastatic potential)." (PMID 31109147, 2019). "We further reasoned that it would be necessary to adjust for chromosome 3 loss, which is known to be associated with BAP1 biallelic inactivation and metastatic risk in uveal melanoma." (PMID 31748560, 2019). "Another major gene, BAP1, has been involved in uveal melanomas, both through somatic alterations and germline variants." (PMID 31262050, 2019).
uveal melanoma (continued). "BAP1-TPDS is associated with an increased risk of developing uveal melanoma (UM), cutaneous melanoma (CM), malignant mesothelioma (MMe), renal cell carcinoma (RCC), meningioma, cholangiocarcinoma, multiple non-melanoma skin cancers, and BAP1-inactivated nevi." (PMID 31382694, 2019). "Uveal melanoma (UM) is the most common primary eye cancer and frequently leads to metastatic death, which is strongly linked to BAP1 mutations." (PMID 29317634, 2018). "Deleterious BAP1 mutations are associated with deficiency in melanocytic differentiation in uveal melanoma (UM) and cancer metastasis." (PMID 28812986, 2017). "In uveal melanomas, somatic inactivating mutations of BAP1 have been highly associated with onset of metastatic behavior thus suggesting a potential novel target for therapy." (PMID 28302097, 2017). "This study evidently implicates mutational inactivation of BAP1 in the acquisition of metastatic competence in uveal melanoma." (PMID 28544818, 2017). "A germline BAP1 mutation in paraganglioma was first discovered in a family whose medical history included the presence of various tumors, in particular malignant uveal melanoma, mesothelioma, and breast cancer." (PMID 28187001, 2017). "Recently, researchers have identified mutations in BAP1 gene, located on chromosome 3, and this gene seems to play a major role in tumor progression in uveal melanoma." (PMID 28645290, 2017). "Loss of BAP1 was also associated with the epithelioid histological type of melanocytic neoplasms including uveal melanoma and epithelioid atypical Spitz tumor and the presence of epithelioid cells in uveal melanoma." (PMID 28404968, 2017). "Loss of nuclear BAP1 protein was associated with aggressive metastatic phenotype and poor prognosis in uveal melanoma." (PMID 28404968, 2017). "CYSLTR2 mutations occur in 3% of uveal melanoma patients, and 50% of cases associate with BAP1 mutations." (PMID 29156643, 2017). "Harbour and co-workers showed inactivating BAP1 mutations in majority of metastasizing uveal melanomas." (PMID 28404968, 2017). "It is of interest to note that a minority of uveal melanoma patients exhibited germline BAP1 mutations, suggesting a possible role of mutations of this gene as a genetic factor predisposing to cancer development." (PMID 29156643, 2017). "BAP1 mutations were detected in 32.5% of uveal melanoma and 2.4% of cutaneous melanoma according to the TCGA database." (PMID 28404968, 2017). "BAP1 functions as a classic two-hit tumor suppressor gene and is somatically mutated in ccRCC, uveal melanoma." (PMID 27819754, 2017). "Previous studies have demonstrated the robustness and reliability of BAP1 IHC in detecting double hit inactivation/mutation in multiple tumours including uveal melanoma, cutaneous melanoma, malignant mesothelioma, and renal cell carcinoma." (PMID 26982343, 2016). "The progression and metastasis of uveal melanoma and MABNs have been associated with a loss of function of BAP1, which is located on chromosome 3." (PMID 27057633, 2016). "BAP1 has been found to be frequently mutated in uveal melanoma and in one case of melanoma associated with a nevus of Ota." (PMID 27057633, 2016). "A number of genes are involved in the progression of cutaneous melanomas, but BAP1 is the only prevalent gene associated with malignant progression in uveal melanoma, melanomas associated with a nevus of Ota and MABN." (PMID 27057633, 2016). "Familial uveal melanoma: Recently, an autosomal dominant hereditary cancer syndrome has been described in some patients with germline BAP1 mutation." (PMID 27800275, 2016). "Our data, confirmed and expanded by others, showed that germline BAP1 mutations are also associated with uveal melanoma, renal cell carcinoma and other malignancies, causing a condition that we named “BAP1 cancer syndrome”." (PMID 27447750, 2016).
uveal melanoma (continued). "The mutations in BAP1 were the most common events not only in MM patients but also in other types of cancer, such as uveal melanoma and renal cancer." (PMID 27187383, 2016). "While our findings will need to be confirmed in other models, this is potentially of clinical significance, as HDAC inhibitors are currently being investigated in clinical trials for uveal melanoma in which BAP1 mutations are common." (PMID 25970771, 2015). "Clinically BAP1 mutation was initially linked to more aggressive, metastasizing uveal melanoma, whilst subsequent cell models suggested that BAP1 loss induces a stem cell-like phenotype." (PMID 25970771, 2015). "Our results reveal a novel route of transendothelial migration for uveal melanoma cells, and they provide insight into the mechanism by which loss of BAP1 promotes metastasis." (PMID 25506912, 2014). "BAP1 loss is associated with an aggressive metastatic phenotype in uveal melanoma and in renal cancer." (PMID 25536104, 2014). "BAP1 loss in uveal melanoma predicts increased risk of liver metastases after enucleation surgery, thereby highlighting the need for careful patient selection for this radical surgical procedure." (PMID 25536104, 2014). "BAP1 is often mutated or deleted in a range of cancers, most commonly in uveal melanomas, malignant pleural mesotheliomas and clear cell renal carcinomas indicating that it represents a tumour suppressor protein." (PMID 24748658, 2014). "Germline BAP1 mutations have recently been associated with an increased risk of several cancers, including atypical melanocytic tumors and uveal melanoma." (PMID 24743024, 2014). "There are certain genomic abnormalities associated with poor prognosis in uveal melanoma, such as inactivation of BAP1 and loss of an entire copy of chromosome 3 (monosomy 3)." (PMID 23762736, 2013). "Inactivating mutations of BAP1 have been found particularly in uveal melanomas, and as germline mutations that predispose to melanoma and other cancers." (PMID 23762276, 2013). "To study the effects of BAP1 loss in uveal melanoma cells, we initially used siRNA to achieve at least an ~ 80% depletion of BAP1 protein levels." (PMID 23915344, 2013). "BAP1 inactivating mutations are found in cutaneous nevi and melanoma, although considerably less frequently than in uveal melanoma." (PMID 23694694, 2013). "In summary, we demonstrate that BAP1 is necessary for maintenance of melanocyte identity in uveal melanoma cells, and that loss of BAP1 leads to a loss of cell identity and acquisition of a primitive, stem-like phenotype." (PMID 23915344, 2013). "To assess metastatic capacity, we then performed tail vein injections of BAP1-deficient and control uveal melanoma cells in the same mouse strain, and the BAP1-deficient cells formed fewer metastases in the liver and lungs compared to control cells." (PMID 23915344, 2013). "Truncating germline mutations in the tumor suppressor gene BRCA-1 associated protein-1 (BAP1) have been reported in families predisposed to developing a wide range of different cancer types including uveal melanoma and cutaneous melanoma." (PMID 23977234, 2013). "Using scratch assays as a measure of cell motility, BAP1-deficient uveal melanoma cells were less motile than control cells." (PMID 23915344, 2013). "To assess the ability to form tumors in vivo, we created flank tumors in NOD-SCID gamma mice using BAP1-deficient versus control uveal melanoma cells." (PMID 23915344, 2013). "Whole-exome sequencing identified a BAP1 splice mutation located at c.581-2A>G, which leads to a premature truncation of BAP1 in an individual with uveal melanoma." (PMID 23977234, 2013). "BRCA-1 associated protein-1 (BAP1) is a tumor suppressor gene located on chromosome 3, a region that has been linked to uveal melanoma (UMM)." (PMID 23977234, 2013).